FOXO1 (forkhead box O1)
Diseases named in the same sentence as FOXO1 in open-access papers (continued):
Sharing a sentence is not in itself a finding about the gene and the disease.
tumor (continued). "Expression of PAX3::FOXO1 in a regulatable myoblast model causes colony formation in vitro and tumor formation in vivo, while reduced fusion protein expression inhibits both phenotypes." (PMID 37732905, 2023). "Compelling findings provided evidence that TRIB3 linked stress signals are capable of promoting tumor initiation and progression by supporting cancer stemness, which is coordinated with elevated FOXO1 and AKT1 axis." (PMID 35473511, 2022). "Correlating the FOXO1 mRNA expression with different clinic pathological parameters of patients indicated significant association with Age, Age at first live birth, Tumor Size, Lymph Node Status." (PMID 35309123, 2022). "Berberine can also induce mitochondrial dysfunction by significantly upregulating the expression of FoxO1 and FoxO3, thereby causing tumor cell apoptosis." (PMID 36034426, 2022). "In tumor studies, abnormal expression of FOXO1 has been associated with tumorigenesis, tumor-induced angiogenesis and metastasis, tumor cell tolerance to stress, and tumor cell metabolic homeostasis." (PMID 34895065, 2021). "This is evident in the CCL20/CCR6 axis as its overexpression in resistant patients has been associated with increased TFCD4+ infiltration from tumor-infiltrating lymphocytes (TILs) via forkhead box protein O1 (FOXO1)/CEBPB/NF-κB pathway." (PMID 34571731, 2021). "In the spontaneous MMTV-PyMT mammary tumor model, expression of the Akt-insensitive Foxo1 mutant at a low dose was sufficient to deplete tumor-associated aTreg cells and promote CD8+T cell responses, resulting in inhibition of tumor growth." (PMID 33748292, 2021). "We also demonstrated DAC-induced FOXO1 activation upregulates anti-tumor immune response in higher-risk MDS specimens." (PMID 33584800, 2020). "The expression level of FOXO1 was negatively associated with tumor size, and FOXO3a expression was negatively associated with advanced TNM stage and lymphatic metastasis." (PMID 32164722, 2020). "Next, we demonstrated that glycolysis is inhibited in FoxO1-deficient macrophages, which leads to the observed functional changes and the reduced tumor suppression capability." (PMID 32973162, 2020). "Although, the inhibited glycolysis activity with 2-DG increased the co-cultured tumor cell counts, which is similar with FoxO1 deficiency related lower glycolysis level." (PMID 32973162, 2020). "All the results demonstrated that DAC can activate FOXO1 to enhance anti-tumor immune effect in higher risk MDS." (PMID 33584800, 2020). "In a broader context, the proposed model suggests a novel mechanism by which the loss of signaling through ZKSCAN, TFEB, and FOXO1 results in activation of the autophagy-lysosome pathway in tumor suppression." (PMID 32178401, 2020). "As EGFR is highly associated with tumor migration and invasion, we tested effect of FOXO1-miR-96-DUSP1 axis on EGFR signaling." (PMID 31579447, 2019). "The depletion of AKT triggers FOXO1 activation mediated cell cycle arrest or cell apoptosis, however, the phosphorylation of FOXO1 results in the loss of tumor suppressor function." (PMID 30769922, 2019). "In esophageal squamous cell carcinoma, the expression and activation of FoxO1 is influenced by the cross-talk between cancer-associated fibroblasts (CAFs) and tumor cells." (PMID 30646603, 2019). "The association between increased FOXO1 levels and paclitaxel resistance is in keeping with a recent report proposing a tumor suppressive role for Akt-phosphorylated FoxO1 in the cytoplasm." (PMID 30646603, 2019). "PTEN loss leads to AKT- and CDK1- or CDK2-mediated phosphorylation of FOXO1, exclusion of FOXO1 protein from the nucleus, and loss of its tumor suppressor functions in the nucleus 18, 25-27." (PMID 31410199, 2019). "PTEN loss results in activation of AKT, CDK1, and CDK2 kinases, which in turn leads to phosphorylation of FOXO1, exclusion of FOXO1 from the nucleus, and loss of the tumor suppressor functions in the nucleus 18, 25-27." (PMID 31410199, 2019).
tumor (continued). "Specifically, FOXO1 was shown to be associated with alveolar rhabdomyosarcoma as a result of chromosome alteration and is considered as a tumor suppressor." (PMID 28887603, 2018). "Recently it has been demonstrated that Foxo1 repression is associated with enhanced migration of activated Tregs to tumor sites while Foxo1 gain of function leads to quick depletion of activated Tregs, resulting in effective tumor immunity." (PMID 29867972, 2018). "We previously reported a CAF case with monoallelic 13q14 deletion in which the tumor expressed decreased levels of FOXO1 and RB1, both of which were encoded in 13q14, and increased reactive oxygen species (ROS) levels." (PMID 28887603, 2018). "FoxO1, a member of the forkhead O family of transcription factors, is considered a tumor suppressor because of its ability to cause cell cycle arrest and DNA repair." (PMID 22457718, 2012). "In patients with localized tumors, univariate analysis revealed that clinical group, tumor invasiveness (T1 vs.T2), regional lymph node involvement (N0 vs. N1) and FOXO1 fusion were significantly associated with EFS and OS, tumor size and PAX variant with OS only." (PMID 39781573, 2025). "Besides, the mutations of FOXO1 or KMT2D are demonstrated closely related to tumor microenvironment." (PMID 41372946, 2025). "As there are multiple FOXO family isoforms and FOXO3 and -4 were also inactivated in the c-MYC tumors, we could not exclude the possibility that other FOXOs compensated for the loss of Foxo1 tumor suppressor in the double-KO studies." (PMID 39325536, 2024). "Similarly, P. gingivalis Mfa1 and FimA fimbriae also exhibit antiapoptotic activity by upregulating C-X-C chemokine receptor type 4 (CXCR4) and downregulating Forkhead Box O1/3 (FOXO1/3), which are associated with tumor progression." (PMID 38807771, 2024). "Notably, heightened NFIL3 expression in cancer cell lines has been associated with a reduction in apoptosis occurrence and the inhibition of FOXO1 recruitment to specific genes linked to tumor suppression." (PMID 38356719, 2024). "In addition, FOXO1 is worthy of attention as it plays a key functional role as a tumor suppressor in a variety of cancers and is associated with different types of cancers." (PMID 38542784, 2024). "This aligns with the existing data implicating PTEN and FOXO1 in tumor suppression, and that their loss may contribute to cancer initiation and progression." (PMID 38891994, 2024). "Additionally, FOXO1 expression is closely associated with the pathological classification, tumor grade and tumor stage of ccRCC." (PMID 36732762, 2023). "It has been hypothesised that mutations within the DBD may suppress DNA dependent tumour suppressor activities but maintain pro-lymphogenic FOXO1 functions." (PMID 37275916, 2023). "However, loss function of FoxO1 in macrophage exacerbates tumor growth via suppressing the expression of MHCII." (PMID 35993049, 2022). "The low levels of FOXO1 have been linked with tumor progression in several recent studies." (PMID 35309123, 2022). "In addition to its well-known tumor suppressor effects, FOXO1 has been linked to the process of mature B cell development and germinal center dark zone creation." (PMID 36282572, 2022). "CNA-containing genes included oncogenes showing copy number gain such as Yap1, Braf, Foxo1, and Akt3 and tumor suppressors with copy number loss such as Rb1, which may favor tumor growth." (PMID 36376321, 2022). "By focusing on common subcompartment repositioning events between normal and cancer cell lines, we found a shift from active to inactive compartment of the Forkhead box O transcription factor FOXO1, which has been frequently associated with tumor suppressive functions." (PMID 33972523, 2021).
tumor (continued). "Foxo1 was identified as a negative intrinsic regulator of NK cell homing, late-stage maturation, and effector functions, and it can directly target IFN-γ expression; moreover, Foxo1 deficiency increases the NK cell killing capacity of tumor cells ex vivo and the antimetastatic activity in vivo." (PMID 34017344, 2021). "In addition, we demonstrated that underlying the oncogenic and HCC-promoting activity of SAE1 was its ability to upregulate oncogenic effectors of cell cycle progression while downregulating FOXO1-associated tumor suppressing signaling." (PMID 33477333, 2021). "Recent studies have shown that decreased FOXO1 protein was closely linked to onset and progression of many types of human cancer, which indicated that FOXO1 may exert anti-tumor activity and may be a promising therapeutic target 11-14." (PMID 32047567, 2020). "To further investigate the association between tumor-derived FOXO1 and M2 macrophage infiltration in vivo, we established FOXO1-transfected tumor cells (FOXO1(+)) and control (FOXO1(-)) cells and injected them subcutaneously into the left and right dorsal flanks of nude mice (n = 5), respectively." (PMID 33052231, 2020). "As one of FOXO isoforms, FOXO1 is a crucial target of insulin signaling involved in the regulation of metabolic homeostasis along with organismal survival at different levels, suggesting its strong association to angiogenesis and tumor development." (PMID 32364530, 2020). "Consistent with this hypothesis, tumor associated macrophages that have reduced FOXO1 expression exhibit increased M2 polarization, which is thought to enhance tumor growth." (PMID 31849924, 2019). "Because of their anti-proliferative and pro-apoptotic functions, and the fact that conditional deletion of FOXO1/2/4 alleles in adult mouse tissues leads to the appearance of lymphoblastic thymic lymphomas and haemangiomas, FOXOs have been considered to be tumour suppressors." (PMID 29484124, 2018). "Importantly, EphB4 receptor tyrosine kinase signaling has been associated with oncogenic Pax3:Foxo1 fusion protein expression and involved in aRMS tumor progression." (PMID 28817624, 2017). "The loss of FoxO3 may also be affecting other tumour-suppressive functions for which FoxO1/4 cannot fully compensate." (PMID 26764572, 2016). "Although our data suggest a role for FoxO3-mediated inhibition of apoptosis in restraining Myc-driven tumour development, we suspect that loss of FoxO3 may also be affecting other tumour-suppressive functions for which FoxO1/4 cannot fully compensate." (PMID 26764572, 2016). "It was hypothesized that PAX3-FOXO1 expression from the PAX3 control sequences was insufficient to cause ARMS formation, and downstream regions of the FOXO1 locus may be required to induce sufficient PAX3-FOXO1 expression to induce tumor development." (PMID 23206814, 2012). "Additionally, oncogenic fusion genes such as PAX3:FOXO1 have been implicated in suppressing interferon signaling pathways and reducing the expression of antigen presentation machinery, further impairing immune recognition of tumor cells." (PMID 41007114, 2025). "Notably, directly opposing the concept of FoxO1 being a tumor suppressor, ~ 46% of FoxO1 mutations involve sites close to T24, a phosphorylation site for negative regulation, making this site unrecognizable for Akt, and subsequently reducing FoxO1 nuclear export." (PMID 39533662, 2025). "Investigation of FOXO1 inactivation (indicated by immunohistochemical staining for FOXO1 p-S256) in upper urinary tract urothelial carcinoma revealed that increased FOXO1 phosphorylation was observed in tumor tissue and was associated with increased invasiveness." (PMID 37174744, 2023).
tumor (continued). "The expression analysis of pathological stages showed that only FOXO1 expression was significantly associated with tumor stage, while miR-9-5p and CPEB3 gene expression were less associated with clinical stage, implying that FOXO1 may have a potential indicative role in pathological grading." (PMID 35805200, 2022). "Therefore, we hypothesize that DBD mutations may selectively disrupt DNA-dependent tumor-suppressor activities while preserving other FOXO1 functions beneficial to B lymphoma cells." (PMID 35079069, 2022). "Notably, the low FOXO1 protein level was associated with higher tumor grade." (PMID 27835585, 2016). "Indeed, recent results have implicated that FOXO1 has a tumor-suppressing role in OS." (PMID 26344693, 2015). "It has recently been shown that the E2F1 and FoxO1 transcription factors physically associate to control expression of the pro-apoptotic Apaf1 gene in vitro, but the effects of this complex in suppressing tumor onset in vivo is completely unknown." (PMID 25907958, 2015). "Cancer-associated fibroblasts in the cavernous sinus secrete IGF1 under regulation of the transcription factor FOXO1, which binds to receptors on tumor cells to activate proliferation." (PMID 42119924, 2026). "Co-deletion of both GFI1 and FOXO1 largely rescues NK cell differentiation, identifying a critical GFI1-FOXO1 axis required for protection against tumour metastasis." (PMID 42020400, 2026). "Patients with RMS have diverse symptoms and prognosis based on tumor sizes, tumor anatomical locations, histological subtypes of the tumors and genetic testing of paired-box-forkhead box O1 (PAX-FOXO1) fusion gene." (PMID 41584037, 2026). "Of note, some of these Pax3::Foxo1 target genes are hypomethylated and others are hypermethylated between FP and FN tumours, and similarly some are underexpressed and some are overexpressed between these tumour groups." (PMID 39812007, 2025). "Here, we report that silencing FOXO1 leads to elevated ROS levels in tumor cells, which reduces tumor cell proliferation and survival under oxidative stress conditions." (PMID 41124013, 2025). "Pre-treatment samples showed a tumour-specific variant in 14/18 patients, including PAX3::FOXO1 fusion in 10/18." (PMID 39797974, 2025). "FOXO1 has been shown to exert tumor-suppressive effects by inducing cell cycle arrest and apoptosis." (PMID 41185082, 2025). "In many cancers, FOXO1 acts as a tumor suppressor by regulating key genes involved in cell proliferation and cell death." (PMID 41298573, 2025). "Traditionally, FoxOs were considered as tumor suppressors since FoxO1, FoxO3a, and FoxO4 triple knockout mice have a strong cancer‐prone phenotype." (PMID 39533662, 2025). "Overexpression of Sirt1 reduces FOXO1 acetylation, lowers androgen synthesis enzyme levels, and effectively decreases brain androgen levels, thereby delaying tumor progression." (PMID 40075208, 2025). "FOXO1, a member of the forkhead protein O family, functions as a tumor suppressor by modulating cell differentiation and proliferation and by participating in DNA damage repair." (PMID 41458598, 2025). "Although there is cell cycle regulation of Pax3::Foxo1 expression resulting in intercellular heterogeneity within these mouse FP RMS tumours, our results suggest that the overall long‐term Pax3::Foxo1 expression pattern contributes to DNA methylation." (PMID 39812007, 2025). "Due to the abnormal over-proliferation of cancer cells, KSHV upregulates forkhead box protein O1 (FoxO1) and FoxO3, endowing tumor cells with strong antioxidant capabilities." (PMID 40349096, 2025). "PAX3::FOXO1/sgTrp53 tumors occurred unilaterally, with an average tumor-free survival time of 100 days and a 40% penetrance rate." (PMID 40523919, 2025). "Given its high expression in certain tumor tissues and its inhibition of several tumor suppressor genes like FOXO1, p73, and WRN, SIRT1 is believed to promote tumorigenesis." (PMID 39944690, 2025).
tumor (continued). "Pediatric RMS, especially the alveolar subtype with PAX3:FOXO1 or PAX7:FOXO1 fusions, often exhibits a notably immune-suppressing environment that impairs effective anti-tumor immune responses." (PMID 41007114, 2025). "Although FoxO1's participation in stemness maintenance is known, very little has been described about how FoxO1 targets affect cell viability and tumor growth in the context of solid tumors." (PMID 39533662, 2025). "Specifically, the loss of FOXO1 increased apoptosis in HCT116 and MDA-MB-231 cells treated with H2O2 (100 μM), which was partially reversed by overexpressing G6PD or adding NAC, while overexpression of FOXO1 alone significantly decreased tumor cell apoptosis." (PMID 41124013, 2025). "FoxO1 has context‐specific tumor suppressor or oncogenic character in myeloid and B cell malignancies." (PMID 39533662, 2025). "Multivariate analysis of the COG cohort identified older age (≥10 years) and tumor size >5 cm as independent adverse prognostic factors for EFS, and for OS in addition to tumor size, tumor invasiveness (T2) and PAX3::FOXO1 variant." (PMID 39781573, 2025). "Forkhead box O1 (FoxO1) is recognized as a tumor suppressor that represses growth, metastasis, and chemotherapy resistance in multiple malignancies, including HCC." (PMID 40301310, 2025). "Age, IRS group, tumor size, site and invasiveness, nodal status and fusion type (PAX7:: vs. PAX3::FOXO1) were significantly associated with OS." (PMID 39781573, 2025). "The lncRNA LYPLAL1-DT suppresses the β-catenin/WNT system and acts as a tumor suppressor, and this lncRNA is induced by FOXO1." (PMID 40724972, 2025). "Both mechanisms appear to converge on the critical inactivation of PI3K-AKT and subsequent activation of FOXO1, highlighting this axis as a central node for GnRH-mediated anti-tumor effects." (PMID 41458598, 2025). "FoxO1 tumor suppressor activity in some DLBCL cases is further supported by the fact that its ectopic activity, induced by Akt or SYK inhibitors, leads to apoptosis induction in these cells." (PMID 39533662, 2025). "We knocked down the endogenous FOXO1 in tumor cells to minimize its impact on the experimental outcomes." (PMID 39783838, 2025). "Overall, moderate agreement (κ = 0.44, 95% CI: 0.11–0.77) was demonstrated between the presence of Myf6 lineage and high Pax3::Foxo1 expression, implicating an interaction between Myf6 lineage and Pax3::Foxo1 during the development of these FP RMS tumours." (PMID 39812007, 2025). "This inactivation limits FOXO1’s regulation of tumor suppressor genes, thereby promoting tumor progression." (PMID 40396172, 2025). "Hypoxic conditions in tumours can suppress forkhead box O1 (FoxO1) activity, impairing its binding to the CIITA promoter and reducing MHC‐II transcription, consequently promoting immune evasion and tumour progression." (PMID 40673641, 2025). "Our clinical correlation analysis revealed that patients with positive FOXO1 expression had a better prognosis, suggesting its potential tumor-suppressive function in EOC pathogenesis." (PMID 41458598, 2025). "For tumor size, tumor invasiveness (T1 vs. T2) and FOXO1 fusion partner (PAX3 vs. PAX7) a significant correlation was observed for OS." (PMID 39781573, 2025). "A contrasting scenario is cancer-induced cardiac wasting, where 6 weeks of progressive endurance running in female tumor-bearing mice increased FoxO1 phosphorylation, thereby sustaining adaptive autophagy while preventing maladaptive remodeling." (PMID 40861274, 2025). "Collectively, Sora promotes the differentiation but not the proliferation of Treg cells, leading to the expansion of tumor-infiltrating immunosuppressive Treg cells by modulating the VEGFR/ Akt/Foxo1 pathway in CD4+ T cells, thus conferring Sora resistance." (PMID 39743020, 2025).